SOCS2 (suppressor of cytokine signaling 2)
Diseases named in the same sentence as SOCS2 in open-access papers (continued):
Sharing a sentence is not in itself a finding about the gene and the disease.
chronic eosinophilic leukemia (1 paper, 2013). "SOCS3, but not SOCS2, was also upregulated in a chronic eosinophilic leukemia bearing PCM1-JAK2, highlighting its role as a central signalling target of JAK2 translocation neoplasia." (PMID 23372669, 2013).
ductal breast carcinoma (1 paper, 2003). "In ductal breast carcinoma, SOCS-2 and CIS gene expression was particularly strong in tumour cells within the ducts, which were isolated from the reactive stroma by the myoepithelial barrier." (PMID 12888825, 2003).
encephalitis (1 paper, 2019). An acute inflammatory process affecting the brain parenchyma. "SOCS2−/− mice showed an increased inflammatory infiltration in the brain and spinal cord when compared with WT, which only exhibited moderate encephalitis." (PMID 31949423, 2019).
endometrial cancer (1 paper, 2023). Primary or metastatic malignant neoplasm involving the endometrium (mucous membrane that lines the endometrial cavity). "Abundant CpG islands were found to exist in the promoter region of SOCS2 through bioinformatics analysis, and a previous study indicated that SOCS2 CpG islands showed hypermethylation in endometrial cancer." (PMID 37085288, 2023).
essential thrombocythemia (1 paper, 2022). A chronic myeloproliferative neoplasm that involves primarily the megakaryocytic lineage. "Unlike mutant N-Ras-mediated Socs2 downregulation, several hematopoietic malignancies driven by other oncogenic mutations demonstrate upregulated SOCS2 expression, such as JAK2V617F-positive essential thrombocythemia (ET), BCR/ABL-positive CMLs and FLT3-ITD AMLs." (PMID 35352806, 2022).
gastritis (1 paper, 2020). Inflammation of the stomach. "We show that H. pylori positive gastritis patients express significantly higher SOCS3, but not SOCS1 and SOCS2, levels compared to H. pylori negative patients." (PMID 33023610, 2020).
glomerulosclerosis (1 paper, 2017). A hardening of the kidney glomerulus caused by scarring of the blood vessels. "PAS staining demonstrated that SOCS2 overexpression led to a decrease of glomerulosclerosis and renal interstitial fibrosis." (PMID 29207635, 2017).
Huntington disease (1 paper, 2021). Huntington disease (HD) is a rare neurodegenerative disorder of the central nervous system characterized by unwanted choreatic movements, behavioral and psychiatric disturbances and dementia. "Two recent studies described that SOCS2 is involved in autophagy in myocardial I/R and Huntington’s disease, but the underlying molecular mechanisms for SOCS2 regulating autophagy are unclear." (PMID 34819832, 2021). "SOCS2 is shown to be upregulated in Huntington’s disease and involved in regulating autophagy by functioning as an E3 ligase." (PMID 34819832, 2021).
Hyperglycemia (1 paper, 2025). An increased concentration of glucose in the blood. "SOCS2 is involved in GDM, as SOCS2-knockout mice exhibit hyperglycemia during pregnancy." (PMID 40362828, 2025).
hypothyroidism (1 paper, 2014). Abnormally low levels of thyroid hormone. "Hypothyroidism impaired body weight gain and decreased circulating levels of IGF-I and biological markers of GH-STAT5b signaling activity in the liver (i.e., mRNA levels of IGF-I, ASL, SOCS2, CIS, and CYP2C11)." (PMID 24816529, 2014).
in situ ductal carcinoma (1 paper, 2003). "SOCS-2 gene expression more significantly increased in the cancerous cells (+135% vs normal duct, P<0.05) of in situ ductal carcinoma, as well as in the tumoral area of infiltrating carcinoma (+50% vs normal duct, P<0.05)." (PMID 12888825, 2003).
keloid (1 paper, 2024). An irregularly shaped, elevated mark on the skin caused by deposits of excessive amounts of collagen during wound healing. "As shown in, at the protein level, the expression of PLIN2 and AKR1C3 was significantly increased in keloid samples compared to normal samples, whereas the expression of SOCS2, SLC38A1, and SNCA was significantly decreased." (PMID 39834787, 2024). "In summary, we identified AKR1C3, PLIN2, SOCS2, SLC38A1, and SNCA as characteristic genes associated with ferroptosis in keloids through comprehensive transcriptomic data analysis." (PMID 39834787, 2024). "Additionally, as depicted in, at the mRNA level, there was also a significant increase in the expression of PLIN2 and AKR1C3 in keloid samples, and a significant decrease in the expression of SOCS2, SLC38A1, and SNCA." (PMID 39834787, 2024). "In keloids, the expression of SOCS2 is downregulated, which may affect the scar healing process by modulating inflammation, cell proliferation, and other pathways." (PMID 39834787, 2024).
laryngeal squamous cell carcinoma (1 paper, 2021). A squamous cell carcinoma that arises from the larynx. "For instance, increased expression of miR-196b inhibits SOCS2 in laryngeal squamous cell carcinoma resulting in tumor progression and poor prognosis outcomes." (PMID 34605350, 2021).
liver cirrhosis (1 paper, 2022). "Two diagnostic models including SOCS2, LCAT, FTCD, KRT17, PBK, and CBX2 expression were proved to accurately separate HCC from normal and liver cirrhosis samples in this study." (PMID 36159831, 2022).
liver failure (1 paper, 2019). A liver disease characterized by the liver losing or has lost all of its function. "For instance, in a model of liver failure with acetaminophen overdose, SOCS2−/− mice had more necrosis, oxidation, and proinflammatory cytokines in the liver than WT mice." (PMID 31949423, 2019).
lung squamous cell carcinoma (1 paper, 2018). "Importantly, the Kaplan–Meier Plotter analysis revealed that lung adenocarcinoma patients (n = 1104) with low SOCS2 expression levels had worse overall survival (p < 0.001), whereas the survival curve of patients with lung squamous cell carcinoma (n = 444) is unrelated to the expression of SOCS2." (PMID 29559623, 2018).
lymph node metastasis (1 paper, 2018). "In particular, the decreased expression of SOCS2 significantly associated with advanced pathological stage, lymph node metastasis and shorter overall survival in lung adenocarcinoma patients." (PMID 29559623, 2018). "Further analysis indicated that the expression of SOCS2 negatively correlated with clinical stage (p = 0.045) and lymph node metastasis (p = 0.013) especially in patients with lung adenocarcinomas." (PMID 29559623, 2018). "The expression levels of SOCS2 significantly correlated with clinical stage, lymph node metastasis, histological subtype and survival time." (PMID 29559623, 2018).
lymphoid leukemia (1 paper, 2021). A malignant lymphocytic neoplasm of B-cell or T-cell lineage involving primarily the bone marrow and the peripheral blood. "Moreover, SOCS2 expression predicted poor outcomes in pediatric AML, while high levels of SOCS2 correlated with progression for both myeloid and lymphoid leukemias." (PMID 34604264, 2021).
Macrosomia (1 paper, 2025). "Here, we review this pathophysiology and pose the hypothesis that an aberrant response to cytokine receptor activation, particularly involving the suppressor of cytokine signaling 2 (SOCS2), contributes to GDM and fetal macrosomia." (PMID 40362828, 2025).
macular degeneration (1 paper, 2020). Loss of vision in the central portion of the retina (macula), secondary to retinal degeneration. "Among them, four Hyper-LGs (CKB, PPP3CA, TGFB2, and SOCS2) overlapped with risk genes in the category of “macular degeneration” in the PHGKB." (PMID 32209064, 2020).
mantle cell lymphoma (1 paper, 2024). Mantle cell lymphoma is a rare form of malignant non-Hodgkin lymphoma affecting B lymphocytes in the lymph nodes in a region called the ``mantle zone''. "In mantle cell lymphoma (MCL), SENP1 knockdown increases apoptosis by suppressing JAK-STAT5 signal transduction and increasing the expression of tumor suppressor cytokine signaling 2 (SOCS2)." (PMID 38389923, 2024).
meningoencephalitis (1 paper, 2020). Inflammation of the meninges and brain, generally secondary to an infectious cause. "Unlike HSV-1 infection, SOCS2 KO mice have worsened meningoencephalitis compared to wild-type animals during BHV-5 infection, indicating that SOCS2 protein has a protective effect on intracranial BHV-5 infection." (PMID 33072096, 2020).
metastasis (1 paper, 2021). The spread or migration of cancer cells from one part of the body (where they first appeared) to another. "Moreover, SOCS1, SOCS2, and CISH were associated with lymphatic metastasis, and SOCS1-7 was associated with distant metastasis in KIRC." (PMID 34926570, 2021).
migraine (1 paper, 2021). "Among SOCS transcripts, the best AUC values have been detected for SOCS2, suggesting its superior function as a peripheral marker for migraine." (PMID 34646121, 2021).
myelitis (1 paper, 2019). An inflammatory process affecting the spinal cord. "Brain tissues from SOCS2−/− mice showed a mild to moderate myelitis at this time point." (PMID 31949423, 2019).
narcolepsy (1 paper, 2007). A sleep disorder characterized by a tendency for excessive sleepiness during the day which occurs even after adequate sleep in the nighttime. "It is not known if the observed decrease in SOCS2 expression in the narcoleptic dogs may be associated with an increased cytokine response since an involvement of immunological component is obscure in the canine model of narcolepsy." (PMID 17521418, 2007).
plasma cell tumors (1 paper, 2007). "Slow-appearing plasma cell tumors expressed Socs1 and Socs2 but v-Abl-accelerated plasma cell tumors expressed 4–5 times as much." (PMID 17764563, 2007).
primary immunodeficiency (1 paper, 2023). "SOCS2 was mainly upregulated in mismatch repair, sulfur metabolism and DNA replication and downregulated in primary immunodeficiency, NLR, and BCR signalling pathways." (PMID 37559129, 2023).
squamous cell carcinoma (1 paper, 2018). A carcinoma arising from squamous epithelial cells. "Moreover, we observed decrease in SOCS2 levels in tumours compared to normal tissues in 61/64 (95%, p = 0.011) of adenocarcinoma and 19/28 (67%, p = 0.995) of squamous cell carcinoma." (PMID 29559623, 2018).
staphylococcal infection (1 paper, 2024). An infection caused by Staphylococcus. "Nonetheless, most studies have concluded that the activity of SOCS2 is limited and redundant, in contrast to our field observations of higher predisposition to staphylococcal infections in animals carrying the SOCS2 variant in a homozygote state." (PMID 39185412, 2024).
Turner syndrome (1 paper, 2022). Turner syndrome is a chromosomal disorder associated with the complete or partial absence of an X chromosome. "This is illustrated by correlation of a SOCS2 polymorphism with a positive response to GH therapy during puberty, and increased adult height of children with GH deficiency and Turner syndrome after long-term rhGH treatment." (PMID 36398696, 2022).
type 1 diabetes (1 paper, 2018). "Recent data have also shown that Socs2 deletion protects against streptozotocin-induced type 1 diabetes in adult male mice, possibly through increased β-cell hypersensitivity to GH." (PMID 29343614, 2018).
ZIKV infection (1 paper, 2020). "In contrast, BRAF and SOCS2, a FLT3 interactor, were unregulated upon ZIKV infection." (PMID 33148605, 2020).
tumor (110 papers, 2003 to 2026). "Dysregulated signaling promotes the expression of inhibitory receptors, such as PD-L1, on tumor cells and tumor-associated macrophages (TAMs), and upregulates suppressor of cytokine signaling 2 (SOCS2) in DCs, contributing to TME reprogramming." (PMID 41359111, 2025). "XH Zhou found that HCC-derived exosomes induced the overexpression of microRNA-761 (miR-761) in HCC, and reprogrammed the tumor microenvironment via targeting the SOCS2/JAK2/STAT3 pathway, which activated the tumor-associated fibroblasts (CAFs)." (PMID 41567219, 2025). "DC-mediated T cell priming and adaptive antitumoral immunity is enhanced in SOCS2-deficient mice, resulting in reduced tumor burden." (PMID 36398696, 2022). "Many studies have shown that METTL3 promotes tumor growth and aggressiveness by regulating the mRNA decay and stability or mRNA translation of numerous tumor-associated genes, such as SOCS2, BATF2, EGFR, TAZ, MAPKAPK2, and DNMT3A." (PMID 35456475, 2022). "What’s more, the level of SOCS2 was negatively associated with miR-767-5p expression, and positively correlated with circNOL10 expression in BC tumor tissues." (PMID 33397365, 2021). "It has been reported for CML that SOCS2 is overexpressed in advanced tumor stages and that SOCS2 expression is dependent on the Bcr-Abl mutation." (PMID 31775389, 2019). "Similar to STAT5-deficient livers, hepatic transcription of tumor SOCS2 was also found decreased in GHRLD mice." (PMID 25566190, 2014). "Our results showed that high SOCS2 expression is associated with increased overall survival and after adjusting for age, lymph-node status, estrogen receptor status and tumor grade, high SOCS2 expression remained an independent predictor for good prognosis." (PMID 17651480, 2007). "Additionally, KEGG pathway results revealed that SOCS2 was implicated in numerous classical tumor‐related pathways, including arginine biosynthesis, the cell cycle, neural ligand receptor interaction, primary bile acid biosynthesis, and ribosomes." (PMID 39307915, 2024). "Taken together, we found that the SOCS2 may be associated with the malignant biological behavior of tumor." (PMID 38071211, 2023). "The tumor diagnostic model was formulated as follows: logit (P-HCC) = -2.534 – 1.240 * SOCS2 expression level - 1.320 * LCAT expression level + 0.335 * FTCD expression level – 1.911 * KRT17 expression level + 4.422 * PBK expression level + 2.006 * CBX2 expression level." (PMID 36159831, 2022). "The tumor diagnostic model was formulated as follows: logit (P-HCC) = 6.906 - 0.494 * SOCS2 expression level - 1.250 * LCAT expression level – 0.493 * FTCD expression level + 0.602 * KRT17 expression level + 1.950 * PBK expression level + 7.243 * CBX2 expression level." (PMID 36159831, 2022). "It still remains to be shown whether high SOCS2 expression per se is causative for the differences in tumor differentiation and prolonged overall survival." (PMID 17651480, 2007). "Suppression of SOCS2 expression might be associated with inhibition of tumor cell proliferation." (PMID 29622769, 2018). "Our team recently discovered that high expression of miR-181b in HB cells promotes tumor metastasis by inhibiting the expression of SOCS2, leading to the activation of the JAK2/STAT5 signaling pathway and EMT." (PMID 41393242, 2025). "It downregulated several potential oncogenes (e.g., AEBP1, MIAT) and genes linked to GBM proliferation and migration (e.g., SOCS2, HCP5) while modulating Wnt signaling and up-regulating tumor suppressor genes (e.g., SPRY4, BEX2)." (PMID 39874307, 2025). "SOCS2 (Suppressor of Cytokine Signaling 2) modulates cytokine signaling and ferroptosis of tumor cells, potentially shaping the ALL tumor microenvironment." (PMID 40375984, 2025).
tumor (continued). "Conversely, restoring SOCS2 expression or inhibiting JAK2/STAT5 signaling can suppress tumor metastasis in HB." (PMID 41393242, 2025). "Altogether, POU6F1 or lncRNA-CASC2 can activate SOCS2 signaling to promote ferroptosis and further inhibit tumor growth in nude mouse." (PMID 38267746, 2024). "For example, in HCC, as METTL3 expression increases, SOCS2 undergoes increased m6A modifications to promote tumor development." (PMID 38613157, 2024). "In contrast, DNMT3a-TET2 crosstalk silences tumor suppressors (i.e., P15, SOCS2) through a corepressor complex with HDAC2 along with increased promoter DNA methylation." (PMID 38528605, 2024). "miR-3648 promotes tumor cell progression by suppressing the expression of cytokine signaling 2 (SOCS2), a member of the SOCS family that negatively regulates cytokine receptor signaling." (PMID 38983267, 2024). "Subcutaneous tumor models were established, in which the expressions of Ki-67, SOCS2, and GPX4 were detected by immunohistochemistry." (PMID 38267746, 2024). "IHC demonstrated that Ki-67 and SLC7A11 expression in tumor tissues were decreased in response to erastin treatment, but SOCS2 expression was elevated." (PMID 38267746, 2024). "It regulates tumor proliferation and apoptosis by targeting SOCS2, indicating its potential as a therapeutic target." (PMID 38983267, 2024). "The investigators reported that aberrant methylation of SOCS2 gene correlates with transcriptional silencing of both breast and ovarian cell lines and that SOCS2 gene suppressed the growth of both tumor cells." (PMID 38895458, 2024). "A positive correlation between survival time and SOCS2 expression level in HCC tumor patients was also found in our study." (PMID 38515461, 2024). "Western blot results in tumor tissues showed that erastin can increase the expression of SOCS2, but inhibit SLC7A11 and GPX4 expression, which can be further promoted by POU6F1 or lncRNA-CASC2 overexpression." (PMID 38267746, 2024). "Specifically, we found that upregulation of miR-181b in HB cells promotes tumor metastasis by inhibiting the expression of SOCS2, which leads to activation of JAK2/STAT5 signaling and subsequent promotion of EMT related to invasion." (PMID 37955014, 2023). "As a member of the SOCS family, the suppressor of cytokine signaling 2 (SOCS2) is present in numerous types of tumor progression." (PMID 37346073, 2023). "Conversely, restoration of SOCS2 expression or inhibition of JAK2/STAT5 signaling can suppress tumor metastasis in HB." (PMID 37955014, 2023). "m6A modification induced SOCS2 mRNA degradation, which abolished the tumor suppressive roles of SOCS2 in liver cancer." (PMID 37926706, 2023). "Clinicopathological correlation analysis revealed that low expression of SOCS2 was significantly correlated with tumor metastasis (P = 0.046) and vascular invasion (P = 0.028), associated with poor prognosis." (PMID 38071211, 2023). "Taken together, these results showed that miR-194-5p acts as a sponge for SOCS2 which acts as a tumor suppressor gene downregulated in PDAC." (PMID 36539807, 2022). "To verify that miR-194-5p promotes tumor progression, we used both bioinformatic methods and mRNA-seq to identify SOCS2 as the target gene of miR-194-5p." (PMID 36539807, 2022). "Consistent with previous studies, we observed lower expression of SOCS2 in human tumor tissues than in normal tissues." (PMID 35037826, 2022). "For instance, several down-regulated PCGs in the LL-like tumor samples, including SOCS2, CADM2, SH3TC and ENC1, are previously reported as potential tumor suppressors." (PMID 35939448, 2022). "In view of the well-defined tumor-suppressing function of SOCS2 by inhibiting Jak2/Stat3 signaling, we detected the effects of miR-877-3p on Jak2/Stat3 signaling in GC." (PMID 35600882, 2022). "Collectively, these results further confirm that miR-1307-3p/SOCS2 axis is essential for the circDIDO1-mediated tumor suppression effect in GC." (PMID 35864511, 2022).